USP20 (ubiquitin specific peptidase 20)
Diseases named in the same sentence as USP20 in open-access papers (continued):
Sharing a sentence is not in itself a finding about the gene and the disease.
cardiac hypertrophy (1 paper, 2025). "Cardiomyocyte‐specific deficiency of USP20 exacerbated cardiac hypertrophy and dysfunction, whereas cardiomyocyte‐specific overexpression of USP20 ameliorated cardiac function upon hypertrophy." (PMID 40192103, 2025). "Pathological examination further confirmed the aggravation of myocardial hypertrophy and fibrosis resulted from deficiency of USP20." (PMID 40192103, 2025). "Functionally, USP20 deficiency exacerbates cardiac hypertrophy induced by either angiotensin II (Ang II) or transverse aortic constriction (TAC), whereas USP20 overexpression alleviates hypertrophic responses." (PMID 40192103, 2025). "Additional research is necessary to investigate the involvement of PTMs in the USP20‐mediated pathogenesis of cardiac hypertrophy." (PMID 40192103, 2025). "Taken together, these results suggest that USP20 overexpression improves cardiac hypertrophy and dysfunction." (PMID 40192103, 2025). "Cardiomyocyte‐enriched USP20 regulates the K63‐linked ubiquitination of STAT3, and the cardiomyocyte‐specific USP20‐STAT3‐CARM1 axis exerts a protective role in cardiac hypertrophy." (PMID 40192103, 2025). "This study investigates the role and mechanism of deubiquitinating enzyme (DUB) ubiquitin‐specific protease 20 (USP20) in cardiac hypertrophy." (PMID 40192103, 2025). "Targeting USP20 through cardiac‐specific gene therapy presents a promising strategy for the treatment of cardiac hypertrophy." (PMID 40192103, 2025). "Further investigations are needed to elucidate the other mechanisms by which cardiomyocyte‐derived USP20 regulates cardiac hypertrophy." (PMID 40192103, 2025). "In this study, we identified USP20 specifically enriched in cardiomyocytes, as a crucial factor down‐regulated in pathological cardiac hypertrophy." (PMID 40192103, 2025). "In this study, we identified cardiomyocyte‐enriched USP20 as a protective regulator in human and mouse cardiac hypertrophy." (PMID 40192103, 2025). "Our data substantiate the protective role of USP20 in pathological cardiac hypertrophy, and present novel translational potentials by targeting USP20 and its downstream axis with small molecule inhibitor." (PMID 40192103, 2025). "Next, we investigated whether USP20 played an important role in transverse aortic constriction (TAC)‐induced cardiac hypertrophy in both USP20 CKO mice and USP20fl/fl mice." (PMID 40192103, 2025). "We demonstrate that the cardiomyocyte‐specific USP20‐STAT3‐CARM1 axis plays a protective role in cardiac hypertrophy, suggesting that targeting USP20 with cardiac‐specific gene therapy could be a promising strategy for treating cardiac hypertrophy." (PMID 40192103, 2025). "Interestingly, KEGG enrichment analysis indicated that the JAK‐STAT pathway is significantly involved in USP20‐mediated cardiac hypertrophy." (PMID 40192103, 2025). "We next evaluated whether USP20 overexpression has a therapeutic effect on myocardial hypertrophy." (PMID 40192103, 2025). "Therefore, our results suggest that USP20 may prevent cardiac hypertrophy through STAT3 as a substrate." (PMID 40192103, 2025). "To assess whether USP20 can improve cardiac hypertrophy by regulating STAT3, we administered wild type and USP20 CKO mice with or without STAT3 inhibitor stattic (10mg kg−1, i.g.)." (PMID 40192103, 2025).
cervical cancer (1 paper, 2022). A primary or metastatic malignant neoplasm involving the cervix. "Specifically, different from the observation in cervical cancer that USP20 regulates the stability of p62 in TNFα mediated NF-κB activation, USP20 act as a DUB that negatively regulates NF-κB signal transduction in ATL." (PMID 35508480, 2022).
esophageal cancer (1 paper, 2025). A primary or metastatic malignant neoplasm involving the esophagus. "They noticed that elevated USP20 expression is associated with higher levels of MCL1 protein in esophageal cancer cell lines." (PMID 39931465, 2025).
heart failure (1 paper, 2025). Inability of the heart to pump blood at an adequate rate to meet tissue metabolic requirements. "Alternatively, overexpression of USP20 significantly reduced heart failure‐related serum biomarkers, such as serum ANP and serum BNP." (PMID 40192103, 2025). "Our findings reveal a novel cardiomyocyte‐specific USP20‐STAT3‐CARM1 (coactivator‐associated arginine methyltransferase 1) axis that regulates cardiac hypertrophy and heart failure, and position USP20 as a potential therapeutic target for pathological cardiac hypertrophy and heart failure." (PMID 40192103, 2025). "Importantly, similar results of USP20 were observed in human hypertrophic myocardium of patients with heart failure." (PMID 40192103, 2025). "Thus, USP20 overexpression mitigates Ang II‐induced cardiac remodeling and heart failure." (PMID 40192103, 2025).
HTLV infection (1 paper, 2020). "Finally, ubiquitin-specific peptidase 20 is an enzyme that has been shown to negatively regulate NFkB in an HTLV infection." (PMID 32526950, 2020).
hypopharyngeal carcinoma (1 paper, 2025). Carcinoma, predominantly squamous cell, arising from the epithelial cells of the hypopharynx. "Compared with non‐metastatic tumours, metastatic hypopharyngeal carcinoma tissues exhibited significantly higher levels of USP20 and CTSL, accompanied by elevated N‐cadherin and decreased E‐cadherin expression, indicative of an enhanced EMT phenotype." (PMID 41261048, 2025). "Together, these findings suggest that USP20 and CTSL are closely linked to metastatic progression and poor clinical outcomes in hypopharyngeal carcinoma, highlighting their potential as prognostic biomarkers and therapeutic targets." (PMID 41261048, 2025). "Correlation analysis revealed a strong positive relationship between USP20 and CTSL expression in hypopharyngeal carcinoma samples (R = .62, p = .0012)." (PMID 41261048, 2025).
Insulin resistance (1 paper, 2024). Increased resistance towards insulin, that is, diminished effectiveness of insulin in reducing blood glucose levels. "The mice injected with si-Usp20 lost weight without reducing their food consumption significantly; therefore, the indications of insulin resistance were treated, and their metabolic level was increased." (PMID 39173829, 2024).
leukemia (1 paper, 2026). A malignant (clonal) hematologic disorder, involving hematopoietic stem cells and characterized by the presence of primitive or atypical myeloid or lymphoid cells in the bone marrow and the blood. "Genetic knockdown of USP20 via shRNA significantly induced apoptosis and suppressed proliferation in AML cells in vitro, while in vivo depletion of USP20 attenuated leukemia development and improved overall survival." (PMID 41800264, 2026).
metabolic syndrome (1 paper, 2024). A cluster of metabolic risk factors for CARDIOVASCULAR DISEASES and TYPE 2 DIABETES MELLITUS. "Hence, USP20 is a promising target for treatment of metabolic syndrome." (PMID 39173829, 2024).
pancreatic adenocarcinoma (1 paper, 2023). "In contrast, high USP20 expression may be associated with longer OS in GBM, pancreatic adenocarcinoma (PAAD), and thymoma (THYM)." (PMID 36874086, 2023).
prostate carcinoma (1 paper, 2017). A carcinoma that arises from epithelial cells of the prostate gland. "The SNCA, USP20, and SNRPA1 genes were selected for prostate cancer with the accuracy of 73.33 and precision of 66.67." (PMID 29563929, 2017).
Sepsis (1 paper, 2025). Sepsis is defined as life-threatening organ dysfunction caused by a dysregulated host response to infection. "In the present study, we aim to investigate the role of USP20 in sepsis‐induced cardiomyopathy and explore the underlying mechanisms." (PMID 41042219, 2025).
cancer (16 papers, 2014 to 2026). A tumor composed of atypical neoplastic, often pleomorphic cells that invade other tissues. "The protein expression of β-catenin is positively associated with USP20 in patient samples and various cancer cell lines." (PMID 37311739, 2023). "Besides its involvement in hypoxia signaling, USP20 is also reported to be dysregulated in cancer, and its depletion is known to be associated with increased chromosomal aberrations, malignant transformation, and tumor growth." (PMID 31208103, 2019). "By characterizing metabolic adaptations in TKI-resistant tumors, we identify ubiquitin-specific peptidase 20 (USP20) as a critical resistance driver that enables cancer cells to evade ferroptosis." (PMID 41844497, 2026). "As a member of the largest DUB subfamily, USP20 plays a pivotal role in various cancers by stabilizing oncogenic proteins." (PMID 41261048, 2025). "Pan‐cancer analysis across TCGA datasets revealed that USP20 and CTSL expression were particularly associated with unfavourable prognosis in HNSCC, among other cancer types." (PMID 41261048, 2025). "We used bioinformatics to analyze the expression and prognosis of USP20 in pan-cancer and explore the relationship between USP20 expression and immune infiltration, immune checkpoints, and chemotherapy resistance in CRC." (PMID 36874086, 2023). "We investigated the expression of USP20 in pan-cancer by applying the TIMER online tool to obtain RNA-seq data in TCGA." (PMID 36874086, 2023). "Previous studies revealed that cancer stem cells (CSCs) were responsible for tumor chemotherapy resistance, metastasis, and recurrence, we then investigated the functions of USP20 in HCC stemness." (PMID 38124786, 2023). "Through analysis of TCGA database, we found that USP20 was differentially expressed in a variety of cancers compared with normal tissues, suggesting that it is a tumor-associated molecule." (PMID 36874086, 2023). "A recent study reported that USP20 stabilizes β‐catenin and activates Wnt/β‐catenin signaling pathway, thereby promoting the migration, invasion, and proliferation of cancer cells." (PMID 38124786, 2023). "Scoring revealed that the protein expression of USP20 was down-regulated in CRC tissues compared with the cancer adjacent tissues." (PMID 36874086, 2023). "Overall, these results suggest that USP20 overexpression may promote CRC metastasis to promote cancer progression in CRC." (PMID 36874086, 2023). "Several reports have examined the role of USP20 in cancer, and the results have been controversial." (PMID 36874086, 2023). "The deubiquitinating enzyme USP20 (ubiquitin specific peptidase 20) regulates the deubiquitination of β-catenin and controls its stability, and as a result, positively regulates the tumorigenesis and chemoresistance in which cancer." (PMID 37914721, 2023). "Furthermore, ubiquitin specific peptidase 20 (USP20) regulates the deubiquitination of β-catenin to control the invasion and migration of cancer cells." (PMID 33482821, 2021). "Indeed, USP20 deubiquitinates and stabilizes its associated protein, hypoxia-inducible factor (HIF)-1α, resulting in the promotion of cancer cell proliferation, invasion, and metastasis." (PMID 27058415, 2016). "The knockdown of USP20 caused the sensitization of two different cancer cell lines to cisplatin, strongly suggesting that an inhibitor against USP20 may function as a cancer therapeutic drug." (PMID 25605410, 2015). "Consequently, modulating USP20 activity can be of unique cancer therapy." (PMID 36237424, 2022). "USP20 mediates the deubiquitination and stabilization of CTSL, thereby promoting epithelial‐to‐mesenchymal transition and cancer stem cell renewal, ultimately enhancing metastatic potential and chemoresistance." (PMID 41261048, 2025). "Ubiquitin‐specific protease 20 (USP20), a deubiquitinating enzyme (DUB), is a pivotal regulator in cancer biology, stabilizing substrates that drive proliferation, metastasis and therapy resistance." (PMID 41261048, 2025).
cancer (continued). "Collectively, these findings demonstrate that USP20 promotes EMT, migration, drug resistance and cancer stemness through upregulating CTSL expression, highlighting its potential as a therapeutic target in HNSCC." (PMID 41261048, 2025). "Molecular correlation analysis showed that USP20 significantly and positively correlated with the expression of multiple immune checkpoints such as ADORA2A and CD160 in a variety of cancers." (PMID 36874086, 2023). "Research indicates that USP20 triggers the activation of multiple pathways, including Wnt, MAPK, HIF1, NF‐κB, cell cycle checkpoints and other signalling cascades, thereby promoting the progression of various cancer types." (PMID 41261048, 2025).
tumor (13 papers, 2014 to 2026). "USP20 may promote tumor metastasis and is associated with immune infiltration and drug resistance in CRC." (PMID 36874086, 2023). "In T‐cell acute lymphoblastic leukaemia (T‐ALL), USP20 has been identified as a super‐enhancer‐regulated driver gene that promotes tumour cell survival by deubiquitinating and stabilizing HIF1A." (PMID 41261048, 2025). "This TINCR–miR-199a–USP20 axis contributes to tumor resistance to T cell killing, whose effects can be reversed by either TINCR knockdown and/or PD-L1 blockade effects." (PMID 41154428, 2025). "Through multiple mechanisms, USP20 maintains the activity of oncogenic signalling pathways and participates in tumour cell hypoxia adaptation, proliferation and invasion." (PMID 41261048, 2025). "Immunofluorescence staining further confirmed decreased expression of stemness markers SOX2 and ALDH1 in USP20‐silenced tumours compared to controls." (PMID 41261048, 2025). "The effects of CTSL or USP20 depletion on tumour biological behaviour were evaluated through various in vitro and in vivo assays." (PMID 41261048, 2025). "We examined the consequences of USP20 mutants on tumor growth, and found that only USP20 (WT) promoted xenograft growth." (PMID 38124786, 2023). "Animal studies demonstrated that USP20 depletion significantly inhibited tumor growth and increased the antitumor efficacy of OXA." (PMID 38124786, 2023). "We examined the consequences of USP20 mutants on tumor growth, and found that USP20‐WT and S132D/S368D promoted xenograft growth." (PMID 38124786, 2023). "We require more evidence to support USP20 as a potential tumor therapeutic target or combine USP20 inhibitors with other drugs in cancer treatment." (PMID 35508480, 2022). "We believe that USP20 as a tumor therapy target is expected to become a reality in the clinic with the in-depth exploration of the role of USP20 in tumor progression." (PMID 35508480, 2022). "The development of clinical drugs for USP20 will also provide a new opportunity for tumor treatment." (PMID 35508480, 2022). "In our review, we highlight the different mechanisms of USP20 in various tumor types and demonstrate that USP20 regulates the stability of multiple proteins." (PMID 35508480, 2022). "Fourth, presently, the impact of USP20 on tumor development occurs only in cells or animal models, and clinical samples must be further verified." (PMID 35508480, 2022). "Fifth, through searching currently available literature, we have summarized the role of USP20 in the regulation of cellular proliferation, migration, tumor growth, and metastasis." (PMID 35508480, 2022). "Recently, many breakthroughs have been made in clarifying the role of USP20 in regulating cell proliferation, migration, tumor growth, and glucose metabolism by regulating different signaling pathways." (PMID 35508480, 2022). "This question becomes more relevant since a recent study showed that CLASPIN, the human homologue of Mrc1, is stabilised by the deubiquitinating enzyme USP20 during checkpoint activation and that USP20 suppresses xenograft tumor growth." (PMID 26201080, 2015). "With a defective intra-S-phase checkpoint in the USP20-depleted cells, we would expect that these cells would exhibit genome instability leading to enhanced tumor growth." (PMID 25326330, 2014). "The USP20 inhibitor GSK2643943A exhibits significant anti‐tumour activity." (PMID 41261048, 2025). "Additionally, USP20 modulates diverse biological processes by stabilizing both oncogenic and tumour‐suppressive proteins." (PMID 41261048, 2025). "USP20 knockdown markedly decreased tumour formation rates and stem cell frequency." (PMID 41261048, 2025). "This suggests that USP20 may affect the tumor immune response by regulating the expression of immune checkpoints." (PMID 36874086, 2023).
tumor (continued). "Considering that the ceRNA mechanism is one way in which lncRNAs participate in the regulation of tumor progression, we assessed whether USP20 can be regulated by TINCR through the ceRNA mechanism." (PMID 36725842, 2023). "This suggests that USP20 may regulate tumor immunity by regulating the expression level of specific immune checkpoint genes." (PMID 36874086, 2023). "Finally, we summarize the alterations of USP20 in multiple human cancers and discuss novel findings regarding the potential of this enzyme as a tumor therapeutic." (PMID 35508480, 2022). "CASKIN2, TLE2, USP20, SPRN, ARSG, MIR106B, and MIR98 were considered to be substantially expressed in the low-risk group, suggesting that these genes may be PAAD tumor suppressor genes." (PMID 35077391, 2022). "Third, the mechanism by which USP20 promotes tumor progression in this review has been elucidated in a few types of cancer cells, but the mechanism is unclear in most cancer cell lines that highly express USP20." (PMID 35508480, 2022). "Inhibition of USP20 expression promotes chromosome instability and xenograft tumor growth." (PMID 25326330, 2014). "Our study as well as those of others’ has demonstrated that USP20 may ensure genome stability and suppress xenograft tumor growth." (PMID 25326330, 2014). "We speculate that USP20 may promote tumor progression by promoting lymph node metastasis." (PMID 36874086, 2023). "Therefore, regulating the activity of USP20 is a novel tumor treatment." (PMID 35508480, 2022). "However, USP20 as a tumor therapeutic target has its limitations." (PMID 35508480, 2022). "The different roles of USP20 may attribute to the heterogeneity of different tumor types." (PMID 35508480, 2022). "Thus, it remains open whether USP20 is a tumor suppressor or activator: Cell type-dependent effects are likely to be considered." (PMID 31208103, 2019). "Taken together, these findings suggest that USP20 may function as a tumor suppressor." (PMID 25326330, 2014). "Pharmacological inhibition of USP20 was found to resensitize TKI-resistant tumors to sorafenib, resulting in marked suppression of tumor growth in vivo." (PMID 41844497, 2026). "Our study reveals a novel mechanism in which USP20 competitively interacts with STUB1 to stabilize CTSL and promote tumour progression." (PMID 41261048, 2025). "Consistently, IHC scores of both USP20 and CTSL were significantly elevated in metastatic tumours relative to non‐metastatic tumours in the Harbin cohort." (PMID 41261048, 2025). "To further explore the relationship between USP20 and chemoresistance, we analyzed USP20 expression and the IC50 of chemotherapeutic drugs in tumor cells." (PMID 36874086, 2023). "Taken together, our findings demonstrated a novel function of HERC2/USP20 in coordinating CHK1 activation by modulating CLASPIN stability, which ultimately promotes genome stability and suppresses tumor growth." (PMID 25326330, 2014). "This indicates that USP20 may play a role in regulating the autoimmune process and may be a potential target for inhibiting FOXP3-induced tumor immune escape." (PMID 38806474, 2024). "In the subcutaneous tumor model, downstream signaling molecules were downregulated in the TINCR knockdown group relative to the control group, and there were no significant changes in STAT1 and p-STAT1, and the protein levels of PD-L1 and USP20 were also downregulated." (PMID 36725842, 2023).